JAK2 (Janus kinase 2)
Diseases named in the same sentence as JAK2 in open-access papers (continued):
Sharing a sentence is not in itself a finding about the gene and the disease.
cancer (continued). "We also found that pantoprazole inhibits the activation of the JAK2/STAT3 pathway and that a higher concentration of pantoprazole treatment displayed better efficacy in treating the muscle wasting induced by cancer cachexia by regulating the JAK2/STAT3 pathway." (PMID 28489606, 2017). "JAK2/STAT3 signaling becomes deregulated in most cancers and is over activated in BTICs and GBM." (PMID 29253028, 2017). "Cancer cells could escape the effects of IFN-γ by downregulating or mutating molecules including IFNGR1/2, JAK2, and IRF1." (PMID 29299180, 2017). "Targeting the stroma has gained interest with multiple preclinical and clinical trials targeting SHH, JAK2, and methods of either exploiting the secretory capability of CAFs to enhance drug delivery or inhibiting it to prevent its influence on cancer cell chemoresistance." (PMID 28351381, 2017). "Interestingly, a recent study indicated that the activation of the JAK2/STAT3 signaling pathway plays an important role in cancer cachexia, and the use of AG490, a JAK2 specific inhibitor, can improve the prognosis of cancer cachexia." (PMID 28489606, 2017). "The amount of JAK2 protein increased in STIP1-knocked-down cancer cells after exposure to MG132." (PMID 27409672, 2016). "It has been well studied that p- Janus-activated kinase 2 (Jak2) could activate STAT3, and the Jak2/STAT3 signaling pathway is involved in the development of cancers and EMT." (PMID 27121055, 2016). "Interleukin-6 regulated stem cell-related genes and activated JAK2/STAT3 in cancer cells." (PMID 25797257, 2015). "We found such examples in BRAF and JAK2 kinases, which are involved in cancer pathologies." (PMID 26322316, 2015). "Combinations of JAK2 inhibitors with inhibitors of the hedgehog (Hh) pathway, which plays a role in the maintenance of cancer stem cells, could provide an avenue of targeting stem cell–derived clonal myeloproliferation (which evades JAK2-targeted monotherapy)." (PMID 24598114, 2014). "In human cancer cells, these dual inhibitors block the auto-phosphorylation of Aurora A (Thr-288) and the phosphorylation of the Aurora B substrate histone H3 (Ser-10) and the JAK2 substrate STAT3 (Tyr-705)." (PMID 24930769, 2014). "However, in cancer cells, including breast, ovarian and prostate, the JAK2/STAT3 pathway is constitutively active in the majority of cases." (PMID 24886434, 2014). "Thus, inhibition of constitutive STAT3 activity by synthetic direct inhibitors or the JAK2 inhibitor AG490 has been shown to induce apoptosis of cancer cells." (PMID 24260381, 2013). "Notably, IL-6 is a cytokine that can activate JAK2/STAT3 signaling in cancer cells, which has an important effect on oncogenesis." (PMID 23690956, 2013). "Thus, the anti-cancer activities of Icariside II can be exerted by its pleiotropic effects on the multiple targets including STAT3 as well as JAK2, Src, and anti-apoptotic bcl-2, bcl-xL, survivin and COX-2 in U937 cells." (PMID 22493659, 2012). "Finally, we will present typical examples of aberrant splicing responsible for the deregulation of oncogenic kinases activity in cancers (AuroraB, Jak2, Kit, Met, and Ron)." (PMID 22007291, 2012). "Therefore, actin cytoskeletal signaling is the common target of Cuc family's anti-cancer activity, which can converge on cell survival machinery through JAK2/STAT3-dependent and -independent mechanisms." (PMID 21304528, 2011). "While JAK2 mutation is a common means to stimulate oncogenic STAT activity, perturbations in other signaling networks, such as those mediated by EGFR, IL-6/IL-6R or FLT3, can also contribute to activated STAT signaling in cancer cells." (PMID 21533169, 2011). "In the past several years, cucurbitacins have become a subject of intense investigation because this triterpene family induces cancer cell death and many of them inhibit the phosphorylation of Janus kinase 2 (JAK2) and signal transducer and activator of transcription 3 (STAT3)." (PMID 21304528, 2011).
cancer (continued). "In 2004, an acquired point mutation in the Janus-activated kinase-2 (JAK2) gene was discovered which occurs in >95% of all PV patients and approximately 50% of those with ET or IM, but not in other cancers." (PMID 20617023, 2010). "Thus, cancer cell-specific-targeting of JAK2/STAT3 or combinations with immunotherapy may be required for further evaluation of JAK2/STAT3 signaling as a cancer therapeutic target." (PMID 38297352, 2024). "On the contrary, JAK2 gene amplification may cause persistent activation of the JAK2/STAT3 pathway, which has been linked to survival, proliferation, angiogenesis, resistance to apoptosis, carcinogenesis, and metastasis in many types of human cancer cells." (PMID 38974233, 2024). "Targeting the IL-6/JAK2/STAT3 signaling axis may enhance the effectiveness of cancer therapies." (PMID 39103836, 2024). "In conclusion, several cancers with JAK2/STAT overactivation, either induced by growth factor stimulation or by receptor mutations, could benefit from HSP90 or HSP27 targeting alone or in combination with JAK2 targeting therapies." (PMID 36765939, 2023). "Due to the scarcity of published research in the field of LNK and luminal cancer, we conducted an analysis of the available datasets containing genetic data with the intention of shedding some light on the potential associations among LNK, JAK2, STAT3, STAT5, 14-3-3, and clinical outcomes." (PMID 37834225, 2023). "However, the implication of JAK2 deletion in human cancers has rarely been explored." (PMID 35851582, 2022). "As our analyses were performed in an MPN cohort, it remains to be determined whether similar effects can be observed also in cancer cells without JAK2‐V617F mutation." (PMID 35015307, 2022). "It has been reported that inhibition of the MAPK pathway activates the JAK2/STAT3 pathway, and autocrine Interleukin 6 (IL-6) secretion and subsequent JAK2/ STAT3 activation may represent an unexpected route to overcome targeted inhibition of the MAPK pathway in BRAF mutant cancers." (PMID 36430869, 2022). "This suggested that the JAK2 signaling pathway could be an important target in cancer treatment." (PMID 35207737, 2022). "It has been demonstrated that the JAK2 46/1 haplotype may lead to increased production of inflammatory cytokines and impaired immunity, both of which are key contributing factors in the development of cancers." (PMID 35884495, 2022). "Therefore, targeting Jak2/STAT3 signaling is an important therapeutic option in cancer treatment that may help reduce angiogenesis." (PMID 34833950, 2021). "Therefore, matrine could significantly suppress the phosphorylation levels of JAK2/STAT3 signaling pathway in cancer cells." (PMID 34642304, 2021). "The downregulation of JAK2/NF-κB pathways might mediate the anti-cancer process." (PMID 34034714, 2021). "We hypothesized that AT-I could directly interact with JAK2 to mediate its anti-cancer activity." (PMID 32273843, 2020). "Moreover, a similar antitumor effect was observed for DCZ0858 and the JAK2 inhibitor ruxolitinib, and combining the two could significantly enhance cancer-suppressive signaling." (PMID 32296013, 2020). "One significant example of this crosstalk between cancer cells and the microenvironment is the secretion of cytokines like interleukin-6 (IL-6) by the cancer-associated mesenchymal stem cells that enhance the progression of CRC through the IL-6/JAK2/STAT3 signaling." (PMID 32626705, 2020). "In eukaryotes, JAK2/STAT3 engagement is associated with significant intracellular changes, through which the expression of multiple cytokines and growth factors, cell proliferation, differentiation, and apoptosis occur, which are relevant for cancer progression and drug resistance." (PMID 32565533, 2019).
cancer (continued). "We hypothesize that enhancing these already existing anti-regulatory T-cell responses through therapeutic cancer vaccination with arginase-I and PD-L1 derived epitopes can boost the neo-antigen specific immune response induced by vaccination with JAK2/CALR-mutant epitopes." (PMID 30327655, 2018). "JAK2 is associated with HSP90 as an HSP90 client, and HSP90 inhibitors may suppress JAK2 protein expression in both wild-type and JAK2 inhibitor-resistant mutant cancer cells." (PMID 27409672, 2016). "Thus, it is suggested that targeting JAK2/STAT3 proteins may represent an important therapeutic target for novel cancer therapy." (PMID 26755649, 2016). "Our biochemical and genetic studies clearly demonstrated that Jak2/Stat3, in combination with other IL-6 downstream pathways, contributed frequently and substantially to IL-6 autocrine production in a broad spectrum of cancer cell lines as well as in clinical cancer samples." (PMID 21122157, 2010). "For the first time, we demonstrate that pregnancy-level PRL directly enhances JAK2/STAT3 and JAG1/NOTCH1 signaling in CRC cells, promoting epithelial-mesenchymal transition (EMT) and cancer stem-like protein expression." (PMID 41501898, 2026). "In vitro data was then used to link pregnancy levels of PRL to increased JAK2/STAT3 and JAG1/NOTCH1 signaling resulting in increased epithelial-to-mesenchymal transition (EMT) and cancer cell stem-like protein expression." (PMID 41501898, 2026). "Can inhibit JAK2/STAT3 pathway activation; regulate upstream and downstream indicators; suppress BC cell growth, proliferation, and migration; promote cancer cell apoptosis; and reduce inflammatory responses, thereby exerting anti-BC effects." (PMID 40351419, 2025). "Researchers are developing JAK2 inhibitors (such as ruxolitinib), STAT3 inhibitors, and MYC inhibitors as new treatment options for cancer patients." (PMID 40944417, 2025). "Studies have identified STAT3 as a key regulatory gene within the JAK2/STAT3 pathway, with elevated STAT3 levels observed in different cancer types." (PMID 39940837, 2025). "The molecular docking analysis demonstrated that Melittin preferentially binds to key components of the JAK–STAT pathway, particularly JAK2 and JAK3, leading to the suppression of STAT3 activation and disruption of critical cancer-promoting pathways." (PMID 40243485, 2025). "The primary mechanisms include the suppression of cancer cell growth, promotion of apoptosis and infiltration of CD3 and CD8 T cells, and inhibition of the JAK2/STAT3 signaling pathway, and downregulated PD-L1 expression." (PMID 40642092, 2025). "As a crucial regulator of several proliferative pathways, miR-21 is transcriptionally regulated by the JAK2/STAT3 pathway and elevated in all human cancers." (PMID 39665584, 2025). "The JAK2/STAT3 and ERK pathways are well known for their roles in regulating cell proliferation, survival, migration, and invasion in various cancers." (PMID 40075566, 2025). "Tumour-derived gamma-aminobutyric acid (GABA), a neurotransmitter, inhibits M1 macrophage polarization via the JAK2/STAT3 pathways, thereby promoting cancer progression." (PMID 40407951, 2025). "Oncrasin-72 exerts its activity by inhibiting C-terminal domain phosphorylation of RNA polymerase II in sensitive human cancer cells, thereby activating JNK, suppressing JAK2/STAT3 phosphorylation, and reducing cyclin D1 expression." (PMID 40867324, 2025). "In ovarian cancer, the B7-H3 activation of JAK2/STAT3 was shown to inhibit apoptosis, promoting the proliferation, migration, and invasion of cancer cells." (PMID 40214484, 2025). "Each cancer cell line responds to different AAM-derived factors, but they all funnel through a common JAK2/STAT3 signaling pathway." (PMID 40330466, 2025).
cancer (continued). "It has been shown that matrine can interact with the Src kinase structural domain to inhibit Src activity and downregulate MAPK/ERK, JAK2/STAT3, and PI3K/AKT phosphorylation signaling pathways, thereby inhibiting the proliferation of cancer cells." (PMID 38279206, 2024). "BDNF activates tropomyosin-related receptor kinase B (TrkB), initiating critical signaling pathways such as RAS/MAPK, PI3K/Akt, and JAK2/STAT3, which influence cancer progression and affect cellular processes including proliferation and migration." (PMID 39401197, 2024). "Network pharmacology with the relevant databases and software was used to predict potential targets like CASP3, SRC, ESR1 and JAK2 and pathways such as PI3K-Akt, proteoglycans and focal adhesion in cancer." (PMID 38675723, 2024). "We investigated the role of the IL-6-induced GP130/JAK2/STAT3 pathway in the proliferation, migration, and EMT of KSCs, as these properties are known to promote cell metastasis in cancer." (PMID 38519574, 2024). "OSRE also interact with key oncogenic signaling pathways, including Wnt/β-catenin and JAK2/STAT3, linking them to cancer aggressiveness and therapeutic resistance." (PMID 39594421, 2024). "Lanatoside C, a cardiac glycoside, has been shown to induce apoptosis in cancer cells by suppressing the Janus kinase (JAK)/signal transducer and activator of transcription (STAT)/cytokine signaling (SOCS) (JAK2/STAT6/SOCS2) pathway." (PMID 38527038, 2024). "Lately, some evidences have suggested that various transcription factors, such as JAK2/STAT3, NF-kB, PI3K/AKT/mTOR and MEK1/2/ERK1/2 facilitate the transcription of PD-L1 in cancer." (PMID 38326861, 2024). "Especially, cucurbitacin I (CuI) has an anticancer effect on several types of cancer cells, including lung cancer, glioma, and breast cancer, via inhibiting the JAK2/STAT3 pathway and suppressing the proliferation of cancer cells in vitro and in vivo." (PMID 38370084, 2024). "The results showed that GluOC inhibited the apoptosis of cancer cells via the ROCK1/JAK2/PIK3CA/AKT signalling pathway, promoted cell cycle progression, reduced ROS levels during cancer cell death, and promoted an increase in stem cell properties." (PMID 39054484, 2024). "Our findings also elucidate the mechanism behind anlotinib’s effectiveness, highlighting its role in inhibiting the JAK2/STAT3 pathway, a key regulator in cancer progression." (PMID 39508048, 2024). "The core signaling pathways included pathways in cancer, the PI3K-Akt signaling pathway, and the AGE-RAGE signaling pathway in diabetic complications, involving genes such as AKT1, IL6, JAK2, and MAPK1." (PMID 39338337, 2024). "The JAK2/STAT3 pathway possesses oncogenic functions, including promoting cell growth, enhancing migratory ability, and inducing drug resistance in cancer cells." (PMID 38661644, 2024). "Various chalcone molecules targeting the JAK2/STAT3 axis, such as licochalcone, butein, isoliquiritigenin, 4,3′,4′,5′- tetramethoxychalcone, and Llicochalcone, have been utilized in cancer intervention." (PMID 38686052, 2024). "Activation of the JAK2/STAT3 pathway increases BCa cell growth, promotes EMT, and thereby, invasion and migration of cancer cells, cancer cell stemness and chemoresistance." (PMID 39040042, 2024). "Results with JAK2 and CBP/p300 inhibitors indicated that these pathways contribute to p21 regulation and cancer stemness trait induction." (PMID 38553760, 2024). "Polyphenolic compounds primarily modulate PD-L1 expression by inhibiting key signaling pathways (IFN-γ-induced STAT1, STAT3, JAK2/STAT1, EGFR/Akt, and NF-κB), potentially enhancing the immune system’s capacity to target and eradicate cancer cells." (PMID 38594256, 2024). "These cytokines contribute to the proliferation and migration of cancer cells via the activation of MAPK/ERK, JAK2/STAT3, and PI3K/AKT signaling pathways." (PMID 39220365, 2024).
cancer (continued). "In this study, we have demonstrated that exosomal miR-320d promotes cancer cell metastasis and enhances angiogenesis by downregulating GNAI1 expression and enhancing JAK2/STAT3." (PMID 39695099, 2024). "Reports have illustrated that JAK2/STAT3 signaling upregulates cyclin D2 and stemness-related TFs to persistently maintain CSC stemness in cancers." (PMID 37853437, 2023). "Hsp90 is often overexpressed and associated with poor prognosis in a variety of tumors because it promotes the activation of oncogenic protein kinases, e.g., JAK2/STAT3, PI3K/AKT, and MAPK, facilitating cancer progression." (PMID 37190332, 2023). "JAK2 and SRC overexpression or overactivation are closely related to the development, maintenance and progression of cancers, suggesting that JAK2 and SRC are effective targets for cancer therapy." (PMID 37147297, 2023). "It’s been shown that the persistent activation of JAK 2 and STAT 3 found in many different cancers play essential roles in the development of malignancies." (PMID 38127921, 2023). "A recent study suggested that the knockout of genes in the IFN γ receptor signal pathway (IFNGR1, JAK1, or JAK2) endowed solid tumor cells with resistance to CAR-T cells by reducing the overall binding time and affinity of CAR-T cells with the cancer cells." (PMID 37889543, 2023). "Prior studies have demonstrated a significant involvement of the JAK2/STAT3 pathway in the progression and development of human malignant tumors." (PMID 37766864, 2023). "The JAK2/STAT3 signaling pathway has been shown to play a critical role in injury and cancer in multiple systems." (PMID 37132754, 2023). "The activation of the Janus kinase/signal transducer and activator of the transcription (JAK2/STAT3) signaling pathway promotes the proliferation, migration, and invasion of cancer cells." (PMID 37009004, 2023). "This modification proved indispensable for STAT3’s membrane localization, its interaction with JAK2, STAT3 Y705 phosphorylation, and PRMT6-driven cancer cell metastasis." (PMID 37813837, 2023). "The bioinformatic analysis confirmed that JAK2 and SRC mRNA levels were up-regulated in a variety of cancers." (PMID 37147297, 2023). "According to several studies, MSC-secreted cytokines influence the IL-6/JAK2/STAT3 signaling pathway in cancer cells, which, in turn, can either stimulate or suppress tumor growth or trigger cancer cell apoptosis." (PMID 38132108, 2023). "To understand the mechanism by which PA-CM induced apoptosis in CCA cells, we focused on JAK2/STAT3 signaling, which plays an important role in the growth and survival of many cancers, including CCA." (PMID 38132108, 2023). "In response to hypoxia in cancer cells, HIF-1 increases the expression of JAK2 and STAT3, activating the JAK–STAT pathway and its downstream signaling pathways." (PMID 37373133, 2023). "Several signaling pathways, e.g., the MAPK and JAK2/STAT3 pathways are involved in hsa-miR-135a-mediated cell proliferation and cancer progression." (PMID 37468555, 2023). "JAK2/STAT3 signaling pathway activation takes key parts in carcinogenesis and progression of different kinds of cancers." (PMID 37716993, 2023). "The JAK2/STAT5 pathway is commonly activated in hematologic malignancies, suggesting a broader application of Plek2 inhibitors in cancers." (PMID 36719747, 2023). "The mutational analysis highlighted the likely importance of NRAS, KRAS, JAK2, and CREBBP in pediatric cancer development because these genes are the most commonly mutated genes in pediatric cancer patients." (PMID 36497424, 2022). "The JAK2/STAT3 pathway is responsible for differentiation, cell growth, immune function, and activation, forming solid tumors in different cancers." (PMID 36500220, 2022). "The JAK2/STAT3 signaling pathways also play a critical role in the growth, proliferation, and metastasis of cancers." (PMID 35111269, 2022).